COL1A2 (collagen type I alpha 2 chain)
Diseases named in the same sentence as COL1A2 in open-access papers (continued):
Sharing a sentence is not in itself a finding about the gene and the disease.
infection (17 papers, 2009 to 2025). The state of being infected such as from the introduction of a foreign agent such as serum, vaccine, antigenic substance or organism. "This was accompanied by an increase in tubular injury markers, such as Havcr1, Col1a1 and Col1a2 which encode KIM-1 and type 1 and 2 collagen, respectively; markers that were also identified in our study with PbA infection." (PMID 40661967, 2025). "ART-treated infection impacted the metabolic fraction (with elevated expression of PPARγ and CEBPα), the extracellular matrix (with elevated expression of COL1A2 and HIF-1α), and the inflammatory profile." (PMID 36231066, 2022). "Robust changes in expression of several genes was evident 7 days post-infection; expression of Col1a1, Col1a2, Col3a1, Mmp2, Mmp9 and Lox was significantly increased while expression of Timp3 was significantly decreased." (PMID 24950301, 2014). "Interestingly, the expression of Col1A2, another osteogenic marker, remained unchanged upon infection." (PMID 39467689, 2024). "The contribution of stellate cells—whose markers of the activated form are Acta2, Col1a1, Tagln, Col1a2, Col3a1, Sparc, and Rbp1—changed significantly only during infection with C. sinensis compared to the control (pairwise Kruskal–Wallis test with Benjamini–Hochberg correction, Padj = 0.030)." (PMID 39652576, 2024). "However, two genes (COL1A1 and COL1A2) showed decreasing expression pattern after infection in our study." (PMID 30584247, 2018). "COL1A2, RDH13, and RPS12 were down-regulated following infection with the mutant strain, whereas DEGs related to C-type lectins recognition and signaling mechanisms were up-regulated." (PMID 35215144, 2022). "Also, whereas collagen proteins were downregulated during infection of HFFF-TERTs, the same proteins were upregulated in THP-1s (COL1A1, COL1A2, COL3A1, COL5A1, and COL12A1)." (PMID 38065956, 2023).
connective tissue disorder (15 papers, 2010 to 2025). A disease involving the connective tissue. "OI is a rare, inherited systemic connective tissue disease caused by mutations in COL1A1 or COL1A2 that lead to varying degrees of bone fragility based on the abundance of these collagen types in healthy osteogenic tissue." (PMID 37623368, 2023). "As OI is a connective tissue disorder very often caused by dominant mutations in the genes COL1A1 and COL1A2, gene silencing through RNA interference is a promising field." (PMID 38398378, 2024). "It is an autosomal dominant connective tissue disease causing defects in collagen, associated with two genes, COL1A1 or COL1A2." (PMID 35162892, 2022). "Previous molecular investigations of the patient, all with negative results, included molecular genetic analysis of COL1A1 and COL1A2 on cDNA for the suspicion of arthrochalasis EDS, and an NGS panel for 101 connective tissue disorders." (PMID 31731524, 2019). "Notably, of the 29 children with nFTS with dysmorphic features resembling connective tissue disorders, 7 had VUSs of genes known to be related to connective tissue (BMP4, MATN3, COL2A1, COL11A1, COL1A1, COL1A2, and COL6A3)." (PMID 40524006, 2025).
bone disorder (7 papers, 2015 to 2025). "OI is a brittle bone disorder caused by mutations in COL1A1 or COL1A2 in over 90% of cases; with mutations in many other genes, including SERPINF1, responsible for the other 10% of cases." (PMID 27056980, 2016). "Notably, three patients had VUS in COL1A1, LRP5, and COL1A2 that matched their suspected monogenic bone disorders." (PMID 37076969, 2023).
skeletal dysplasia (7 papers, 2018 to 2025). Any Mendelian diseases that affects growth and development of the skeleton. "Four variants were highlighted in four genes known to cause skeletal dysplasias, namely EBP, INPPL1, COL1A2, and SLC26A2, being the last two characterised by high in utero lethality." (PMID 41153384, 2025). "In Case 7, the affected fetus presented with a very complex and extensive skeletal dysplasia, while a suspected causative compound heterozygous variations in the CANT1 gene was detected, along with the splicing site variant in COL1A2." (PMID 36140746, 2022). "Skeletal dysplasia (SD) is one of the most common inherited neonatal disorders worldwide, where the recurrent pathogenic mutations in the FGFR2, FGFR3, COL1A1, COL1A2 and COL2A1 genes are frequently reported in both non-lethal and lethal SD." (PMID 34789231, 2021).
adenocarcinoma (5 papers, 1988 to 2025). A common cancer characterized by the presence of malignant glandular cells. "In adenocarcinoma, COL1A2, CEBPZ, MED10 and PAWR were overexpressed, suggesting their involvement in advanced disease progression." (PMID 40362431, 2025). "In adenocarcinoma samples, key upregulated candidate biomarkers include COL1A2, CEBPZ, MED10 and PAWR." (PMID 40362431, 2025). "Enrichment pathway analysis identified COL1A2 as a key component involved in the extracellular matrix structural organization pathway, exhibiting significant upregulation in adenocarcinoma compared to CIS." (PMID 40362431, 2025). "For example, the enrichment of extracellular matrix organization pathways and elevated expression of mesenchymal-related genes such as COL1A2 in the adenocarcinoma samples might align with CMS4, known for its stromal remodeling and aggressive phenotype." (PMID 40362431, 2025). "H&E staining shows that the control (Col1a2-TRAMP) mouse prostates uniformly and diffusely displayed invasive adenocarcinomas in the dorsal and anterior lobes, whereas Col1a2-Foxf2-TRAMP mouse prostates showed a spectrum of less advanced lesions in the same lobes." (PMID 36369237, 2022). "Moreover, it was reported that COL1A2 is a potential biomarker for detecting adenocarcinoma." (PMID 40362431, 2025).
Metabolic Disorders (2 papers, 2025). "Our study provides novel insights into the genetic associations of COL1A1 and COL1A2 polymorphisms with BMD and metabolic disorders." (PMID 40507792, 2025). "Genetic variations in the COL1A1 and COL1A2 genes have been linked to bone mineral density (BMD) and metabolic disorders." (PMID 40507792, 2025). "The aim of this study was to evaluate the association between rs1107946 and rs1800012 polymorphisms in COL1A1, as well as rs42524 in COL1A2, with BMD and the risk of metabolic disorders in postmenopausal women." (PMID 40507792, 2025).
epithelial neoplasm (1 paper, 2022). A benign or malignant neoplasm that arises from and is composed of epithelial cells. "Changes in COL1A2 in the ECM microenvironment are often accompanied by stromal invasion and the occurrence of epithelial neoplasms." (PMID 36057263, 2022).
infectious disease (1 paper, 2022). A disorder directly resulting from the presence and activity of a microbial, viral, or parasitic agent in humans. "CTSD (cathepsin D), CD44 (CD44 antigen), and COL1A2 (collagen alpha-2) were associated with the pathways of “infectious disease: viral” and “immune system”." (PMID 36704102, 2022).
COL1A2 also shares sentences with these, for which no sentence is quoted: medulloblastoma (8 papers); genetic disorder (7); osteogenesis imperfecta type 1 (6); cervical cancer (4); gastric tumor (4); Hypertension (4); Marfan syndrome (4); Osteopenia (4); vascular EDS (4); Insulin resistance (3); metastatic disease (3); oral cancer (3); Stroke (3); systemic sclerosis (3); Arthritis (2); Caffey disease (2); campomelic dysplasia (2); chondrosarcoma (2); collagen vascular disease (2); hypertrophic cardiomyopathy (2); idiopathic pulmonary fibrosis (2); kidney damage (2); kidney diseases (2); liver disease (2); lymphoma (2); myopathies (2); neurodegenerative disease (2); rheumatoid arthritis (2); steatosis (2); thanatophoric dysplasia (2).
A further 118 diseases each share a sentence with COL1A2 in 2 papers or fewer.